CCL8 (C-C motif chemokine ligand 8)
Diseases named in the same sentence as CCL8 in open-access papers (continued):
Sharing a sentence is not in itself a finding about the gene and the disease.
cancer (75 papers, 2012 to 2025). A tumor composed of atypical neoplastic, often pleomorphic cells that invade other tissues. "CXCL14+ cancer-associated fibroblasts and CCL8 fibroblast-like cell proportions were higher in both AC and MC tissues than in normal colon tissue." (PMID 37091868, 2023). "CXCL14+ cancer-associated fibroblasts (CAFs) and CCL8 fibroblast-like cell proportions were also higher in AC and MC tissues than in normal tissue." (PMID 37091868, 2023). "For example, CCL8 derived from cancer cells binds to its receptor, C–C chemokine receptor 2 (CCR2) on macrophages, attracting macrophages." (PMID 38976211, 2025). "In response to CCL8, cancer cells secrete CSF1, a key survival and proliferation factor for macrophages, further amplifying the auto‐stimulatory loop." (PMID 40434054, 2025). "The evidence linking CCL8 with cancer development advocate for the development of CCL8‐based therapeutics to inhibit CCL8 activity." (PMID 40545574, 2025). "The elevated concentration of CCL8 not only supports the cancer–TAM crosstalk but also acts as a monocyte chemoattractant." (PMID 40434054, 2025). "More importantly, KCs derived from Ccl8-knockout mice, even pretreated with LvM16 cancer cells, demonstrated a much weaker capacity to activate neutrophils than the wild-type (WT) counterpart." (PMID 40796724, 2025). "Using single cell RNA-sequencing, we observed expression of CCL8, CXCL5, CCL13 and CCL7 in cancer-associated fibroblasts (CAFs)." (PMID 39249543, 2024). "In response to cancer cell secretion of CCL8, the production of colony-stimulating factor-1 (CSF1), a critical factor supporting macrophage survival and proliferation, is stimulated, thus perpetuating the auto-stimulatory cycle." (PMID 39410029, 2024). "ADAMDEC1 + /CCL8 + and CXCL14 + fibroblasts were preferentially co-localized with the IgG + plasma cells, in accordance with the observed presence of CXCL14 + cancer-associated fibroblast and ADAMDEC1 + /CCL8 + fibroblast in MMRp CRC." (PMID 38110959, 2023). "Neutralizing antibody of CCL8 or normal IgG was intraperitoneally administered daily for 5 days, respectively, following implantation of cancer cells." (PMID 35680853, 2022). "CCL8 production in the supernatant of cultured TAMs was also significantly higher than that of cancer cells from primary BrCas (p < 0.01)." (PMID 35680853, 2022). "It was discovered that Siglec-1 is involved in an auto-regulatory loop between TAMs and cancer cells in aggressive BCs, identifying Siglec-1 and C-C Motif Chemokine Ligand 8 (CCL8) expression together as prognostic markers for poor survival." (PMID 33670444, 2021). "Pan-cancer immune profiling suggested that the selected HT parameters elevated the expression of chemo-attractants (CCL8 and CSF1R) and cell adhesion molecules (ICAM and VCAM)." (PMID 33391491, 2021). "Regarding CRC, MCP-2/CCL8 derived from cancer-associated fibroblasts have been shown to stimulate the proliferation of cancer cells, while MCP-2/CCL8 and MCP-3/CCL7 derived from tumor-associated macrophages attract anti-tumor CD4+ and CD8+ T cells." (PMID 34884259, 2021). "Among these IRGs, a two-gene signature consisting of CCL8 and DEFB1 was found to be closely associated with patient prognosis using the cancer genome atlas (TCGA) database." (PMID 32719391, 2020). "ZEB1 in hypoxic cancer cells promoted the migration of TAMs in vitro and altered the expression of multiple chemokines, especially CCL8." (PMID 31263103, 2019). "TNF-α neutralization resulted in a significant reduced CCL8 expression compared with isotype control-treated CM, confirming a role for TNF-α in CCL8 regulation in macrophages exposed to cancer cell CM." (PMID 30930117, 2019). "We next validated these data by incubating PMA-THP1, MDM, and iPSDM with cancer CM and showed elevated CCL8 mRNA and protein levels." (PMID 30930117, 2019).
cancer (continued). "CCL8 treatment of both cancer cell lines significantly upregulated the expression of CSF1 mRNA and protein (Log2FC > 1, p < 0.05), as well as TNF-α and IL-1β." (PMID 30930117, 2019). "The high concentration of CCL8 not only supports the cancer-TAM crosstalk but also acts as a monocyte chemoattractant." (PMID 30930117, 2019). "To assess their function in cancer, we used Pf4creCx3cr1DTR mice, which predominantly deplete CD206hi IMs, including those that express Cxcl13 (for B cell chemotaxis), Cxcl9 and Cxcl10 (for NK and T cell recruitment), as well as Ccl6, Ccl8, Ccl9, and Ccl2418." (PMID 40630529, 2025). "The specific targeting of immune cells suggests that DTCCL8, besides cancers that are responsive to CCL8, may also be effective against other conditions that involve aberrant immune response activation." (PMID 40545574, 2025). "Moreover, heightened levels of CCL8 not only facilitate cancer–TAM communication but also serve as a potent monocyte chemoattractant, enhancing recruitment to the TME." (PMID 39410029, 2024). "Based on bioinformatics analysis of The Cancer Genome Atlas, our study identifies CCL8 as a potential prognostic marker in SKCM and as part of a therapeutic pathway involving M1 macrophages that may be exploited to improve treatment options for patients." (PMID 34844613, 2021). "This may imply the contribution of CCL8 to the molecular mechanism behind the higher recurrence rates of right- compared to left-sided cancers." (PMID 34885960, 2021). "The expression of CCL2, CCL7, and CCL8 in CAF is very important in cancer." (PMID 33182504, 2020). "CCL8-mediated TAM infiltration contributes to hypoxic ZEB1-related cancer progression." (PMID 31263103, 2019). "Additionally, however, we noted a specific set of genes encoding chemokines and cytokines, namely CCL4, CCL8, CXCL10, CXCL11, IFI44L, IDO1, and IFNG that were upregulated in 9p CNG cancers." (PMID 29212506, 2017). "It is plausible that modulation, namely upregulation of CCL8 activity, in combination with other chemokine–cytotoxic drug combinations, may provide a novel strategy for the management of breast and other cancers, depending on their specific responsiveness to specific chemokines." (PMID 40545574, 2025). "Cancer cells secrete chemokines like CCL2/MCP-1, CCL5, and CCL8/MCP-2, which recruit TAMs into the TME." (PMID 40361472, 2025). "Here, we found that TREM2+ TAMs were accumulated in GC, promoting PD-L1 expression and CCL8 secretion through STAT1-enhanced transcription, leading to cancer progression and CD8+ T cell exhaustion." (PMID 41253786, 2025). "In this study, we observed increased macrophage infiltration as well as CCL5, CCL8, and CCL9 expression in AOM/DSS-induced CAC in S100A4Smad4-/- mice, consistent with the pathological changes observed during the inflammation-cancer transition." (PMID 39664586, 2024). "Seven chemokines (CCL18, CCL8, CXCL9, CXCL10, CXCL11, CCL26, and CCL7) showed positive relations in more than 25 cancer types." (PMID 38655053, 2024). "Among chemokines, especially CCL4, CCL5, CCL8, CXCL9, CXCL10 and CXCL11 were markedly positive correlated with LAMP3 expression in most cancers." (PMID 38146591, 2024). "Several studies have confirmed that CCL8 not only promotes proliferation and migration but also enhances EMT and stemness of malignant tumors, which is consistent with our findings that CCL8 is a gene associated with poor prognosis in patients with CC." (PMID 37503314, 2023). "Factors secreted by TAMs, such as TGF-β, VEGF, CCL8, COX-2, MMP9, and MMP2 also contribute to the metastatic properties of cancer cells." (PMID 33352665, 2020). "The discussed group of CC chemokines (CCL2, CCL7, CCL8, and CCL13) have numerous pro-cancer functions, which outweigh their anti-cancer properties." (PMID 33182504, 2020).
cancer (continued). "Hypoxia promoted cancer cell production of more macrophage chemokines, and among all increased chemokines (CCL2, CCL5, CCL8, CCL19, CCL21, and CXCL1), CCL8 was the most increased according to qRT-PCR detection." (PMID 31263103, 2019). "We also identified an auto-regulatory loop between TAMs and cancer cells driven by tumor necrosis factor alpha involving SIGLEC1 and CCL8, which is self-reinforcing through the production of CSF1." (PMID 30930117, 2019). "Indeed, the expression of CCL8, IFIT1, IFIT3, IFI27, MX1, and RSAD2 has previously been considered favorably prognostic in several types of cancer." (PMID 36180872, 2022). "Like IL32, the expression of CCL8 was upregulated in the non-transformed tissue of right-sided cancers, which are known to be more aggressive." (PMID 34885960, 2021). "Due to the recruitment of monocytes, CCL2, CCL7, CCL8, and CCL13 are important in the pathogenesis of many diseases where an important role is played by monocytes and macrophages, in particular atherosclerosis, inflammatory bowel disease, and cancer." (PMID 33182504, 2020). "CCL8, also known as MCF2, acts as an agonist of the CC chemokine receptor type 2 (CCR2) and CCR5, exerting significant function in the process of leukocyte chemotaxis, cancer tumorigenesis and progression, and responds to changes in the pathogenic environment." (PMID 33146700, 2020). "However, despite CCL8's acknowledged role in pathology, inhibition of its activity does not represent a strategy of choice for cancer management." (PMID 40545574, 2025). "Additionally, fluorescence in situ hybridization investigation of human BrCa demonstrated that CCL8 mRNA is found in CD206+ TAMs rather than cancer cells, implying a possible effect of CCL8 produced by TAMs on primary tumors." (PMID 35680853, 2022). "In addition, CCL8 contributes to the migration property and EMT process of cancer cells." (PMID 31263103, 2019).
infection (74 papers, 2006 to 2025). The state of being infected such as from the introduction of a foreign agent such as serum, vaccine, antigenic substance or organism. "Other transcripts encoding pro-inflammatory genes identified as up-regulated in response to sublethal PVM infection and down-regulated in response to L. plantarum include those encoding Ccl2, Ccl8, Cxcl9, Cxcl10, and resistin-like molecule alpha (Retnla)." (PMID 34959580, 2021). "Hence, in mice deficient for CCR2, a receptor for CCL2 and CCL8, the number and size of granulomas, as well as monocyte recruitment at site of infection, are decreased." (PMID 25566510, 2014). "In cattle, RNA-Seq identified key transcriptional markers of infection when M. bovis-infected cows were analyzed, identifying genes such as GMBZ and CCL8 as significantly regulated genes during transition from early to chronic phases of infection." (PMID 41230407, 2025). "Ccl8 is a key gene involved in recruiting immune cells to sites of infection, and Pigr is responsible for transporting immunoglobulins across epithelial barriers to defend against pathogens." (PMID 38932347, 2024). "Four weeks after CnH99 infection or vehicle treatment into Tcra−/− mice, Chemokine C-C motif ligand 8 (CCL8), an endogenous ligand for C-C Motif Chemokine Receptor 5 (CCR5), was significantly upregulated." (PMID 37380639, 2023). "Among 25 tested major chemokines in the hindbrain region of CnH99 infected mice four weeks after infection, only the CCL8 level was significantly increased compared to naive mice." (PMID 37380639, 2023). "In AGM, the expression of Ccl2, Ccl3, Ccl4, Ccl7, and Ccl8 together with Cxcl10 and Cxcl11 also increases during infection, although more rapidly and with a more marked expression in nonpolarized rAM than in hamsters." (PMID 37350967, 2023). "CCL8 is a chemokine which attracts monocytes, lymphocytes, basophils and eosinophils to the site of infection and plays a role in the host’s proinflammtory response." (PMID 33931718, 2021). "Non-human primate survivors of experimental infection displayed upregulation of specific genes, including CCL8, compared to animals that succumbed to infection." (PMID 32670279, 2020). "Various chemokine genes, responsible for the control and recruitment of immune cells to the site of infection (i.e., Ccl2, Ccl4, Ccl5, Ccl7, Ccl8, Ccl12, and Ccl19), were also significantly upregulated in the VACV-Wyeth infected brains on 4 d.p.i." (PMID 30759813, 2019). "Further, we found increased expression of M1 macrophage markers Ccl8, Ido1, and Tnfsf13b in Stat2−/− mice during super-infection when compared to WT mice." (PMID 30337919, 2018). "Recently, diverse functions of CCL8 have been discovered in infection, immunity, and allergic inflammation." (PMID 28057004, 2017). "From the RNA microarray and protein assays, the top single RNA and protein prognostic models at early infection were CCL8 RNA (AUC:0.73) and IP-10 protein (AUC:0.74), respectively." (PMID 27286230, 2016). "Studies demonstrating the contribution of T cells to disease pathogenesis, suggest the recruitment of T cells by chemokines (CCL4 and CCL8) elicited at the site of infection would most likely contribute to the pathogenesis of mycoplasma disease." (PMID 25098731, 2014). "The CCL8 exhibited significantly increased expression at 6–24 h post-infection, and the maximal production was at 12 h post-infection." (PMID 25098731, 2014). "In particular, the significant over-expression of the Csf1, Lefty1, Ccrl2, Gdf3, Il-10 and Ccl8 genes (1.8–5.8 fold increases) was seen at day 9 post-infection." (PMID 23861742, 2013). "We next determined the levels of the Ccr1 agonists Ccl3, Ccl5, Ccl6, Ccl7, Ccl8 and Ccl9 in Ccr1+/+ and Ccr1−/− kidneys after infection." (PMID 22916017, 2012). "CCL2, CCL7, and CCL8, members of the chemokine family, recruit monocytes to sites of injury and infection." (PMID 16805906, 2006).
infection (continued). "In addition to preadipocytes, we also found that mature adipocytes upregulate chemokines during infection, including Ccl8 and Ccl12, which are drivers of monocyte recruitment." (PMID 37644007, 2023). "Examination of chemokine expression at memory showed that infection resulted in sustained upregulation of transcripts encoding for a variety of different chemokines, including CCL1, CCL2, CCL5, CCL8, CXCL9 and CXCL10 compared with control flank skin from the same animals." (PMID 27160938, 2016). "In addition to early induction of CXC chemokines, we also show that induction of genes encoding C-C chemokines namely CCL-2 (MCP-1), CCL8 (MCP-2), CCL12 (MCP-5) and CCL22 (MDC) occurs on D12 and progressively increases between D15 and D21 post infection." (PMID 21249199, 2011). "In our model, some chemokines reported to be part of the "1st and 2nd waves" of chemokine expression by DC cells, specifically Xcl1, Cxcl9, Cxcl16, Ccl1, Ccl2, Ccl3, Ccl4, Ccl5, Ccl7 and Ccl8 are expressed at increased levels in lung i.n. samples at 3 weeks post-infection." (PMID 20942964, 2010). "Furthermore, the expression levels of leukocyte migration‐related cytokines (CCL2 and CCL8) were high in PE but very low in PB, which may be related to the need for cytokines to migrate to the site of infection (pleura)." (PMID 40170555, 2025). "Particularly in dLNs, enhanced production of Ccl8 and Ccl7 was observed in CD1d-KO mice compared with WT mice, which, being monocyte and DC chemoattractants, could enhance the trafficking of those cells infected already as well as potential infection targets." (PMID 39088280, 2024). "Furthermore, most of the pro-inflammatory genes found on this array, which we have previously identified to be increased with 22L infection (such as Cxcl10, Ccl8, Tnf, IL1a, and IL1b), were similarly increased in the absence of TLR2 or C5aR1 signaling during scrapie infection." (PMID 30596651, 2018). "Peaks of activated T and NK cells, B cells, monocyte derived macrophages, CCL8—and CXCL10 production are clearly lower than at the initial infection event." (PMID 39695178, 2024). "HuN2021 infection was accompanied by the upregulation of proinflammatory cytokines, such as IL-6, IL-1β, IL-8, TNF-α, and CCL8, as well as the immunomodulatory cytokines IL-10 and IFN-γ, at the mRNA and protein levels." (PMID 39506759, 2024). "Proteins highlighted in green (e.g., CCL2=MCP-1, CCL7=MCP-3, CCL8=MCP-2, CXCL10=INP10, are proteins known to be elevated in blood after infection for example with M. tuberculosis." (PMID 35145507, 2021). "Lower magnitudes of gene regulation was noted in this study after infection compared to ferrets infected with the H1N1 virus A/California/07/2009 although immune response genes such as CCL2, CCL8, CXCL9, and CXCR1 increased over the time course." (PMID 34267262, 2021). "LTB4/BLT1 axis is required for the synthesis of chemokines that recruits neutrophils (CXCL1 and CXCL2), monocytes (CCL2, CCL8, and CCL7) and T cells (CCL4) at both days 1 and 9 after infection." (PMID 30102746, 2018). "These cytokines (e.g., CCL8, FAS, and IL-6) begin to see significant expression in fatal cases starting at 4–5 days post-infection and are sustained through to the end of infection." (PMID 28930167, 2017). "This was complemented by upregulation of all chemokine genes involved in monocyte recruitment on day 3 in H5N1 infection, whereas only two genes (CCL8 and CXCL10) were upregulated in X-179A infection at this time point." (PMID 28405622, 2017). "Our former research showed CCL8 and CCL11 in mouse brain samples increased gradually in parallel with the rising eosinophil counts in blood after infection." (PMID 26070790, 2015). "Expression of Cxcl9 and Ccl8 was significantly up-regulated in CDC1551-infected cells at both 6 and 24 hpi, compared to infection by HN878, while Il1β was more highly up-regulated at 6 hours than at 24 hours." (PMID 22280836, 2012).